IRF6 (interferon regulatory factor 6)
Diseases named in the same sentence as IRF6 in open-access papers (continued):
Sharing a sentence is not in itself a finding about the gene and the disease.
multiple sclerosis (1 paper, 2022). A progressive autoimmune disorder affecting the central nervous system resulting in demyelination. "An interferon (INF) regulatory factor (IRF6) encoded by the IRF6 was significantly associated with increased risk of liver injury as identified in a case–control study of IFN-β1b-treated multiple sclerosis patients (OR: 8.3, 95% CI: 3.6–19.2; p = 2.3 × 10–8)." (PMID 35250581, 2022). "The results were subsequently confirmed in an independent cohort study of patients with multiple sclerosis in which liver injury was proved with significantly increased aspartate aminotransferase and alkaline phosphatase concentrations for those who carried IRF6 genetic variants." (PMID 35250581, 2022).
nonalcoholic fatty liver disease (1 paper, 2022). "The IRF6 is significantly downregulated in high-fat diet-induced nonalcoholic fatty liver disease, a worldwide epidemic." (PMID 36032143, 2022).
Oligodontia (1 paper, 2022). The absence of six or more teeth from the normal series by a failure to develop. "Interestingly, the oligodontia phenotype was also present in an individual with the IRF6 variant." (PMID 36294409, 2022).
oral cancers (1 paper, 2022). "In skin and oral cancers, IRF6 and GRHL3 have been consistently found to act as tumor suppressors." (PMID 36457487, 2022). "Why the expression and function of IRF6 and GRHL3 are ambiguous in adenocarcinomas and not in skin and oral cancers is not known yet." (PMID 36457487, 2022).
ovarian carcinoma (1 paper, 2024). A malignant neoplasm originating from the surface ovarian epithelium. "First, we only used a small sample for IHC staining, which was insufficient for identifying IRF6 as a diagnostic and therapeutic biomarker for ovarian cancer patients." (PMID 38493179, 2024). "Second, the used dataset was not large enough and should include as many datasets as possible for analysis to determine the accuracy of IRF6 as a biomarker for ovarian cancer patients." (PMID 38493179, 2024). "Finally, we only conducted a preliminary exploration of the role of IRF6 in ovarian cancer." (PMID 38493179, 2024).
Sepsis (1 paper, 2024). Sepsis is defined as life-threatening organ dysfunction caused by a dysregulated host response to infection. "Both the superior performance of the model and the in vitro validation of IRF6-HP in monocytes emphasize that scPAGE2 is effective and robust in the construction of sepsis diagnostic model." (PMID 39710434, 2024). "For instance, in sepsis samples, high expression of HP and low expression of IRF6 were consistently observed, whereas in normal samples, the pattern was opposite with low HP expression and high IRF6 expression across all datasets." (PMID 39710434, 2024). "Our analysis of the single-cell dataset pinpointed that ARG1-CCR7 was a prominent indicator for B cells and T cells in sepsis, while JAM3-PIK3AP1 and IRF6-HP were identified as notable marker for monocytes in sepsis." (PMID 39710434, 2024). "Among the two identified monocyte maker DEPs, only IRF6-HP showed a significantly higher proportion of cells in sepsis samples compared to normal samples (Fisher’s exact test, P-value = 2.18e-14)." (PMID 39710434, 2024). "Elevated IRF6-HP in sepsis monocytes confirmed by both scRNA-seq and an independent cohort using FACS." (PMID 39710434, 2024). "For instance, the expression variance between IRF6 and HP was consistently lower in sepsis samples compared to normal samples across all three platforms." (PMID 39710434, 2024). "Taken together, the four DEPs involved in scGPS2 specifically serve their cell type-related roles in the context of sepsis: the inhibition of ARG1-CCR7 in sepsis B cells and T cells, while the activation of JAM3-PIK3AP1 and IRF6-HP in sepsis monocytes." (PMID 39710434, 2024). "scGPS2, which involved ARG1-CCR7, IRF6-HP, JAM3-PIK3AP1, and TLR9-CLEC4D, demonstrated superior performance in distinguishing sepsis from normal samples across NGS and microarray platforms." (PMID 39710434, 2024). "Notably, IRF6-HP and JAM3-PIK3AP1 showed a significant increase in monocyte cell proportion during sepsis compared to normal samples." (PMID 39710434, 2024).
skin cancer (1 paper, 2022). "While for certain cancer types (e.g., skin cancer) the roles of IRF6 and GRHL3 were found to be consistent (tumor suppressors), the findings were more controversial in others (e.g., female tissues)." (PMID 36457487, 2022). "To clarify these apparent discrepancies on the role of IRF6 and GRHL3 in cancer, we screened breast, colon, lung, and skin cancer cell lines for IRF6, GRHL3, and CDH1 transcripts and compared their levels to them in corresponding control cell lines by qPCR." (PMID 36457487, 2022).
transient cerebral ischemia (1 paper, 2017). "To test further this hypothesis in vivo, we constructed an in vivo murine model of transient cerebral ischemia via MCA occlusion in WT and IRF6 knockdown mice and assessed pioglitazone’s effects upon miR-106a expression 24 hours post-MCA occlusion." (PMID 28526834, 2017).
Waardenburg syndrome (1 paper, 2025). A disorder characterized by varying degrees of deafness and minor defects in structures arising from neural crest, including pigmentation anomalies of eyes, hair, and skin. "Similarly, Waardenburg syndrome (EDNRB) and Van der Woude syndrome 1 (IRF6) have also been reported in autosomal dominant modes." (PMID 41229399, 2025).
tumor (58 papers, 2011 to 2026). "Together, these results suggest that loss of IRF6 expression in EBV-infected epithelial cell tumors promotes tumor formation not only by decreasing epithelial cell differentiation but also by restricting the amount of lytic EBV reactivation." (PMID 40569988, 2025). "Mechanistically, EMT drives repression of Irf6, making the tumor cells less susceptible to the pro-apoptotic effects of T cell-derived TNF-α." (PMID 38378697, 2024). "In 3D BCSC xenografts, IRF6 expression in tumor-associated stromal fibroblasts induced stromagenesis in combination with decreased necrotic growth." (PMID 39273037, 2024). "Data from our in vitro co-culture model suggest that the BCSC-influenced IRF6 upregulation in CAFs is associated with fibroblast encapsulation around tumor clusters." (PMID 39273037, 2024). "For example, SERPINA1 showed close connections to CD8A in CD8+ T cells, CD68 in tumor-associated macrophages, IRF6 in M1 macrophages, NRP1 in DCs, STAT3 and IL17A in Th17 in most digestive cancers." (PMID 37511325, 2023). "After the initial NACT, the downregulated mir-141 was associated with positive regulation of several suggested tumor suppressors, such as IRF6, BCL2, KLHL20." (PMID 35200555, 2022). "In this study, we used autochthonous mouse models, where the expression of Pik3caH1047R oncogene predisposes the skin and oral cavity to tumor development, and show that not only loss of Ripk4, but also loss of its kinase substrate Irf6, triggers rapid SCC development." (PMID 36765696, 2023). "Besides, the results of univariate Cox regression analysis demonstrated that older age, advanced tumor stage, distant metastasis, higher pathological stage and histological grade, and decreased IRF6 expression were associated with shorter OS in ccRCC patients." (PMID 34659554, 2021). "The relative levels of IRF6 and Ki67 proteins in the tumor tissues of the indicated mice were subsequently evaluated by IHC." (PMID 40796729, 2025). "A functional study revealed that PGM1 overexpression counteracts the inhibitory effects of IRF6 overexpression on glycolysis-mediated tumor cell growth." (PMID 40796729, 2025). "IRF6 expression is often silenced by gene methylation in epithelial cell tumors, in which it usually functions as a tumor suppressor." (PMID 40569988, 2025). "The cellular IRF6 transcription factor functions as a tumor suppressor in epithelial cell tumors, including NPC and GC, and promotes differentiation of normal human keratinocytes." (PMID 40569988, 2025). "Transcription factors (TFs) associated with tumor metastasis and progression, such as SOX9, HMGA2, TP63, NFIL3, and IRF6, exhibited high transcriptional activity in the ITGA2hi‐PTC subcluster." (PMID 40985182, 2025). "For example, when over-expressed in NPC cell lines in vitro, IRF6 was found to suppress tumor cell proliferation and the cancer stem cell phenotype, and to increase the sensitivity of cells to chemotherapy treatment." (PMID 40569988, 2025). "Esc tumor cells engineered to re-express Irf6 regained sensitivity to T cell killing upon OT-I co-culture, whereas parental cells lacking Irf6 (Irf6-/-) became resistant to OT-I cell killing." (PMID 38378697, 2024). "As noted by us and others, it is possible that Irf6 modulates tumor cell sensitivity to death stimuli including TNF in part by participating in or reversing the EMT state." (PMID 38378697, 2024). "Our analysis revealed an overlapping pattern associated with acquired resistance to ICB in this different tumor type, supporting the notion that EMT-associated repression of Irf6 is a generalized mechanism of acquired resistance to immunotherapy." (PMID 38378697, 2024). "IRF6 gene expression was higher in the T2 cell line than A3 cell line, demonstrating the importance of the environment proper of the tumor, including radiation and estrogen effects." (PMID 39765744, 2024).
tumor (continued). "IRF6 expression levels were (p < 0.05) significantly higher in the tumor tissue, whereas NFIL3 was in normal adjacent tissues." (PMID 39765744, 2024). "To understand how Irf6 regulates tumor cell-intrinsic resistance to T cell killing, we compared the transcriptomes of control (EV) and Irf6-expressing tumor cells after OT-I co-culture." (PMID 38378697, 2024). "Molecularly, EMT leads to the epigenetic and transcriptional silencing of interferon regulatory factor 6 (Irf6), rendering tumor cells less sensitive to the pro-apoptotic effects of TNF-α." (PMID 38378697, 2024). "We also found that IRF1, IRF3, IRF4, IRF5 and IRF7 were significantly higher in tumor stage III/IV or grade 3/4 compared with tumor stage I/II or grade 1/2, whereas the expression level of IRF6 was lower in tumor stage III/IV or grade 3/4." (PMID 37182129, 2023). "Rather, EMT was associated with epigenetic and transcriptional silencing of interferon regulatory factor 6 (Irf6), which renders tumor cells less sensitive to the pro-apoptotic effects of TNF-α." (PMID 37398248, 2023). "Tumor metastasis is related to the prognosis of the patient; therefore, the effect of IRF6 on CRC cells migration and invasion was explored using transwell method." (PMID 35443865, 2022). "IRF6 exhibited a tumour suppressive profile and its expression was positively correlated with prognosis." (PMID 36741716, 2022). "The transcription factors IRF6 and GRHL3 are both CLP-associated candidate genes as well as prominent tumor suppressors as described in this in vitro study." (PMID 36457487, 2022). "Perhaps surprisingly, we discovered that gRNAs targeting IRF6 were enriched in the screen, indicating a normal function in supressing self‐renewal, consistent with reports of a tumour suppressor role." (PMID 36121125, 2022). "As TRAF3 is a key regulator of B cell survival and is considered to be a tumor suppressor gene of B lymphocytes, IRF6 was presumed to be a tumor suppressor." (PMID 35443865, 2022). "The results showed that MAPK, ERBB, ERK and CREB pathways, which play important roles in the regulation of immune cells in the tumor environment 19-22, were significantly activated in the IRF6 high expression group." (PMID 34659554, 2021). "Decreased expression of IRF6 is also found in highly metastatic nasopharyngeal carcinoma cells, while its overexpression proves to inhibit tumor cell proliferation and growth and enhances their chemotherapeutic sensitivity." (PMID 33941190, 2021). "In view of the fact that tumor progression often affects tumor prognosis, we also investigated the roles of IRF6 in ccRCC prognosis including overall survival time and disease-free survival time." (PMID 33941190, 2021). "As far as DFS is concerned, advanced tumor stage, distant metastasis, higher pathological stage and histological grade, and decreased IRF6 expression were related to shorter DFS." (PMID 34659554, 2021). "After the overexpression of IRF6, the expression of IRF6 in tumor tissues increased, while the expression of KIF20A decreased." (PMID 33941190, 2021). "We therein demonstrated that IRF6, a potential tumor suppressor, is epigenetically silenced by DNA methylation and histone modifications in UC." (PMID 33874979, 2021). "Nude mice subcutaneously injected with IRF6-overexpressed UMUC3 cells exhibited significantly smaller tumor volume and weight than control UMUC3 cells." (PMID 33874979, 2021). "Downregulation of IRF6 has been demonstrated in several cancers, suggesting tumor-suppressor functions." (PMID 34944912, 2021). "Among the others, cells depleted of Lin28A and SNHG14 and overexpressing IRF6 had the smallest tumor volumes." (PMID 32527996, 2020). "Mutations of the IRF6 gene have been reported in 7% of HNSCC patients and down‐regulation of IRF6 has been correlated with tumour invasive and differentiation status of SCC." (PMID 30845357, 2019).
tumor (continued). "Interferon regulatory factor 6 (IRF6) acts as a tumor suppressor and controls cell differentiation in ectodermal and craniofacial tissues by regulating expression of target genes." (PMID 31019894, 2019). "Instead, IRF6 is involved in cell adhesion, motility, control of epidermal precursor proliferation and acts as a tumor suppressor for invasiveness and proliferation." (PMID 31797958, 2019). "Adding to this information, recently, a novel role of IRF-6 was reported implicating IRF-6 in development of exocrine glands as another function besides its role as a tumor suppressor." (PMID 29599126, 2018). "Formalin-fixed, paraffin-embedded tumor sections obtained from patient 4 before (a, c) and after (b, d) the therapy were stained with an anti-Irf6 antibody." (PMID 30545388, 2018). "Formalin-fixed, paraffin-embedded tumor sections obtained from patient 7 before (a, c) and after (b, d) the therapy were stained with an anti-Irf6 antibody." (PMID 30545388, 2018). "RT-qPCR of IRF6 and IL-1β transcripts revealed that both genes were reduced in tumor tissues compared to normal biopsies." (PMID 30089163, 2018). "Formalin-fixed, paraffin-embedded tumor sections obtained from patient 5 before (a, c) and after (b, d) the therapy were stained with an anti-Irf6 antibody." (PMID 30545388, 2018). "Among the nine IRF members, the tumor-suppressive functions of IRF6 have been supported by many studies, in addition to its important function in the development process of palatal fusion." (PMID 28877249, 2017). "siRNA mediated knockdown of IRF6 counteracted Notch-induced differentiation and tumor suppression indicating that IRF6 is an essential mediator of Notch function in keratinocytes." (PMID 26161746, 2015). "In the breast, IRF6 was initially shown to directly interact with maspin, a tumor suppressor, in an immortalized normal mammary epithelial cell line, 1436N1, and have a decreased expression in invasive breast cancer cell lines and breast tumors." (PMID 26161746, 2015). "Furthermore, EMT induces epigenetic and transcriptional silencing of interferon regulatory factor 6 (IRF6), suppressing the responsiveness of tumor cells to TNF‐α‐mediated T‐cell killing." (PMID 41415713, 2025). "IRF6 overexpression inhibits tumor cell growth in vivo and in vitro by attenuating glycolysis." (PMID 40796729, 2025). "Therefore, IRF6 overexpression reversed the ability of TRIM59 to promote glycolysis-dependent tumor cell growth." (PMID 40796729, 2025). "Importantly, IRF6 expression in malignant cells also enhances the host immune response to tumor cells." (PMID 40569988, 2025). "Therefore, we propose IRF6 in stromal fibroblasts to be a significant candidate for further investigation into the mechanism of tumor progression from the CSC niche and, perhaps, also, in the TME." (PMID 39273037, 2024). "However, in order to assess the clinical significance of stromal fibroblast IRF6 activity in a tumor setting, in vivo experimentation was performed." (PMID 39273037, 2024). "Based on the observation of an accumulation of OE CF around BCSC clusters and stromagenesis in BCSC xenografts, it could also suggest that IRF6 expression in fibroblasts may promote the spatial proximity of fibroblast cells with tumor cell clusters." (PMID 39273037, 2024). "To test whether IRF6 indeed constitutes a bona fide tumor suppressor in the skin, we cloned and tested sgRNAs targeting Irf6 and transduced the skin of Pik3caH1047R;LSL-Cas9-GFP mice." (PMID 36765696, 2023). "Next to the expression profiling, we also provide functional evidence that both IRF6 and GRHL3 are tumor suppressor genes: overexpression of IRF6 and GRHL3 in cancer cell lines impaired their proliferation, EMT, migration and induced their differentiation potential." (PMID 36457487, 2022).